H19 (H19 imprinted maternally expressed transcript)
Diseases named in the same sentence as H19 in open-access papers (continued):
Sharing a sentence is not in itself a finding about the gene and the disease.
cancer (continued). "Simultaneously, elevated H19 expression is found in many cancer types, and therefore can be a potential therapeutic target in cancer." (PMID 34713767, 2021). "We first analyzed, by ddPCR expression of several cancer-associated lncRNAs (MALAT1, NEAT1, HOTAIR, H19, PVT1, MEG3) in both FNAs and surgical specimens and selected MALAT1, HOTAIR, and PVT1 as cancer biomarkers." (PMID 33030666, 2021). "It is therefore likely that the effects of H19 on normal and cancer cells are determined by the complex interplay of a pool of cell-specific miRNAs expressed in each cell type." (PMID 34502082, 2021). "From the perspective of the clinical benefits in RHO GTPase-related anti-lncRNA plant-derived natural compounds, credible anti-cancer activity of curcumin was reported through its downregulatory effect on H19." (PMID 34771549, 2021). "An increasing number of studies have revealed that H19 gene up-regulated in almost overall cancer, such as breast cancer, bladder cancer, colorectal cancer, gastric cancer, lung cancer, hepatocellular cnacer, ovarian cancer, pancreatic cancer and so on." (PMID 34310645, 2021). "There are several well-established lncRNAs that have been linked to cancers (e.g., HOTAIR, H19, MEG3, MALAT1)." (PMID 33803619, 2021). "For example, several risk-related SNPs lie within the lncRNA HULC, which is overexpressed in a number of cancers, but also in the lncRNA ANRIL; while some polymorphisms of lncRNA H19 are correlated to bladder cancer." (PMID 33767982, 2021). "While extensive research has been done on the role of H19 lncRNA in cancer metastasis since its discovery, several other lncRNA molecules were recently found to be critical in the regulation of cancer-related EMT." (PMID 35011635, 2021). "For example, carcinoma-associated fibroblasts enhance the stemness and chemoresistance of CRC via transferring the exosomal lncRNA H19; lnc273-31 or lnc273-34 reduction restrains CRC migration, invasion, self-renewal, and chemical resistance of CRC stem cells." (PMID 34858502, 2021). "In patients with proven cancer and expressing low levels of H19, a radical surgical treatment would be an option to be considered." (PMID 33335214, 2020). "Unexpectedly, there was little difference between cancer patients and healthy people with regard to the H19 expression." (PMID 32582694, 2020). "During the past years, along with the fundamental and clinical data highlighting the implication of CSCs in tumorigenicity and cancer progression, more and more studies show that H19 is able to regulate CSCs." (PMID 33291403, 2020). "Collectively, these results demonstrate the involvement of H19 and miR-675 in the enrichment of cancer stem cells." (PMID 32610610, 2020). "In the early years, scientists have tried to establish a unified theoretical model to describe the function of H19 in every stage of cancer." (PMID 33193379, 2020). "LncRNA H19 has been addressed in various cancers as an oncogene, and regulated cell proliferation, apoptosis and migration." (PMID 31918667, 2020). "Further, H19 acts as catalyst that superficially regulates the expression of Wnt targeted genes as well as the MYC gene in many cancers." (PMID 32699525, 2020). "Many previous studies have corroborated the significant role of H19 as an oncogenic molecule in different cancer cells and in tumorigenesis." (PMID 32337223, 2020). "H19 expression is up-regulated in several types of malignant tumors in humans and crucial for the pathogenesis and prognosis of several cancers." (PMID 32272875, 2020). "The most important LncRNA found to be upregulated after penetratin treatment is H19, which is considered to be one of the major genes in cancer, actively involved in all stages of tumorigenesis." (PMID 33213097, 2020). "In these DEGs, several cancer‐associated genes such as HOXC10, THBS1, CDKN2B, PAX2 and H19 were significantly associated with AML biology." (PMID 31794134, 2020).
cancer (continued). "We have already demonstrated the oncogenic role of the H19 gene in breast tumorigenesis, and H19-derived miR-675 has been reported to promote the tumorigenesis of several cancers." (PMID 32610610, 2020). "Patients with 11p15 telomeric domain defects (H19/IGF2:IG-DMR -GOM and UPD) have a higher risk of developing cancer compared to cases presenting centromeric aberrations (KCNQ1OT1:TSS-DMR-LOM mutation and CDKN1C)." (PMID 33101381, 2020). "LncRNA H19 induces the cell migration and invasion by different mechanisms, depending on the cancers." (PMID 32610610, 2020). "Aberrant change in lncRNA H19 expression was shown in various cancers, suggesting a pivotal role of H19 in cancer progression." (PMID 32207861, 2020). "Studies from several cancers show that lncRNA H19 promotes EMT by downregulating E-cadherin through diverse molecular mechanisms, such as stimulating the Wnt/β-catenin signaling pathway, and acting as ceRNA for miRNAs." (PMID 32514245, 2020). "In cancer models, it has been demonstrated that H19 expression is upregulated in non-small cells lung cancer, particularly in gefitinib-resistant cells." (PMID 33291403, 2020). "In cancer progression, H19 has a dual role as an oncogene or a tumor suppressor gene, depending on the cancer type and developmental stage." (PMID 32582694, 2020). "Of note, although the expressions of H19 and miR-675 were generally correlated with that of cancer stem cell markers, some differences existed depending on the considered cell line." (PMID 32610610, 2020). "Base on Cancer Genome Atlas (TCGA) pan-cancer datasets, they specifically examined H19 in pan-cancers and confirm that H19 mediates transcription factors as a microRNA sponge, various new H19 mediated TFs have been discovered." (PMID 33193379, 2020). "Several studies have been used to explain the difference in H19 levels detected in biopsies, while first focusing on the correlation between H19 expression and the differentiated state of cancer cells." (PMID 33335214, 2020). "The overexpression of H19 has been documented in breast, bladder, colon, and other types of cancers." (PMID 32582694, 2020). "Another developmentally important lncRNA, H19, promotes cancer progression in several cancers including breast and is enriched in the ALDHhigh breast CSC populations of TNBCs." (PMID 32244924, 2020). "H19 also functions as a primary template for miR-675, which plays an important role in tumorigenesis and the development of various cancers." (PMID 32977510, 2020). "H19, the first identified lncRNA is involved in the development and progression of many different cancer types." (PMID 33291403, 2020). "H19 also plays a fundamental role in the regulation of autophagy through the induction of the PI3K/Akt/mTOR pathway in human cancers." (PMID 33519750, 2020). "These indicate that H19 acts as an oncogenic factor to promote the progression of these cancers in humans." (PMID 32272875, 2020). "For high-grade cancers in our study, we should try to explain the low levels of H19 by considering other factors." (PMID 33335214, 2020). "Taken together, the ERβ-H19 positive feedback participates in the maintenance of cancer stem cells in this type of cancer under treatment with estradiol." (PMID 32759784, 2020). "H19 is a prominent oncogene in cancer and to this date the only lncRNA that has been investigated in body fluids in the context of PitNETs." (PMID 32498309, 2020). "H19 was first identified as an oncofetal lncRNA and is generally reported to play crucial roles in various types of cancer." (PMID 33115498, 2020). "The cancer-promoting effects of H19 are largely mediated by microRNA-675 (miR-675), a short noncoding RNA transcribed from the first exon of H19 13-15." (PMID 32626524, 2020).
cancer (continued). "It appears that H19 up-regulates various cancer-related mRNA expression level by serving as a ceRNA, and participates in the PI3K–Akt signaling pathway in this manner." (PMID 31164794, 2019). "Long non-coding RNA H19 (H19) is highly expressed in cancers and is considered to highly correlate with the extent of malignant degree." (PMID 31299871, 2019). "Growing evidence indicates that H19 is involved in both the proliferation and differentiation processes of cancer cells." (PMID 30890582, 2019). "Imprinted H19 lncRNA, which plays important roles in development, cancer, and metabolism, modulates Let-7 availability by acting as a molecular sponge and causing precocious muscle differentiation." (PMID 31354514, 2019). "Recent evidence shows that H19 is upregulated in several cancers as, esophageal cancer, hepatocellular carcinoma, ovarian cancer, bladder cancer, and breast cancer." (PMID 31632922, 2019). "lncRNAs play an important role in cancer mainly via their associations with RNA-binding g proteins, which include HOTTIP, MaLAT1, H19, and HOTAIR." (PMID 31827401, 2019). "The BC-819 plasmid used consisted of a double-stranded DNA construct carrying the H19 promoter sequence and the diphtheria toxin A DNA, and was intended to be expressed in cancer cells, which usually express H19 at high levels." (PMID 30937214, 2019). "H19 is an imprinted oncofetal RNA, the expression of which decreases after birth, while the overexpression of H19 lncRNA has been reported in many cancer types in humans." (PMID 31208095, 2019). "Much effort has been made to investigate the link between aberrant lncRNA expression and cancer, including lncRNA H19." (PMID 31016202, 2019). "H19-DTA (BC-819), a DNA plasmid that carries the gene for diphtheria toxin-A, is used to target H19 overexpressing cancer cells under the regulation of the H19 promoter sequence." (PMID 31133028, 2019). "Recently, the Hedgehog signaling pathway, a regulator of differentiation known to participate in cancer development and metastasis, was shown to induce H19 expression." (PMID 31616462, 2019). "The potential predicational role H19 expression for the survival of CRC patients should be determined in various cancers through a more larger database, such as TCGA data." (PMID 30920116, 2019). "Our results indicated that lncRNA H19 had a relatively moderate accuracy in cancer detection and diagnosis." (PMID 31016202, 2019). "Thus, H19 is involved in cancer initiation, development, and progression, suggesting it could be a critical diagnostic and prognostic biomarker as well as a potential novel target in cancer therapy." (PMID 31452627, 2019). "All of the results indicated that H19 had a relatively moderate accuracy in distinguishing cancer patients from all individuals." (PMID 31016202, 2019). "For example, the cancer-related gene WWTR1 was coregulated by H19 and lncRNA TP73-AS1 through four different miRNAs." (PMID 31164794, 2019). "The expression of H19 was significantly up-regulated in hepatic metastases of several types of cancers." (PMID 30890582, 2019). "Mounting evidence has demonstrated that long non-coding RNA (lncRNA) H19 can have both promotive and inhibitory effects on cancer development, revealing a dual role in tumorigenesis." (PMID 31277475, 2019). "H19 overexpression has also been correlated with cisplatin resistance in other cancers, including seminomas and non-small cell lung cancer, where it was associated with evasion of apoptosis." (PMID 32039022, 2019). "H19 functions as a ceRNA to sponge the miRNA let-7 family, leading to an increase in the expression of let-7 targets in several cancers." (PMID 31417644, 2019).
cancer (continued). "If oncogenic transformation involves a reactivation of an inherent developmental program, then it would be expected that the entire IGF-II/H19 functional unit would be involved in the development of cancer." (PMID 31590432, 2019). "The up-regulation of H19 enhances resistance of cancer cells to stress, such as genome destabilization and hypoxia." (PMID 30890582, 2019). "When H19 assays were tested for all individuals with a pretest probability of 50% to have cancer, a positive result would improve posttest probability having cancer to 77%, while a negative result would drop the posttest probability to 28%." (PMID 31016202, 2019). "In the ceRNA network of CRC, H19 up-regulates various cancer-related mRNA by competitively sponging various miRNA, and participates in PI3K–Akt signaling pathway in this manner." (PMID 31164794, 2019). "Even though the significance of H19 in cancer has been recognized for years, its exact role in tumorigenesis is still a subject of controversy as both oncogenic and oncostatic effects have been demonstrated." (PMID 31277475, 2019). "In this study, the link of H19 gene polymorphisms to hepatocarcinogenesis was assessed between 359 HCC patients and 1190 cancer-free subjects." (PMID 31277475, 2019). "The oncofetal H19 is a lncRNA identified as overexpressed in a lot of cancer models compared to normal tissues, and to have multiple roles throughout tumorigenesis." (PMID 31003545, 2019). "Aberrant expression of H19 has been demonstrated in several different cancers; although its exact carcinogenic role is still under debate." (PMID 32039022, 2019). "The long non-coding RNA H19 plays critical roles in cancer occurrence, development, and progression." (PMID 31452627, 2019). "LncRNA H19, an oncogene in diverse cancers, can promote cell proliferation by accelerating cell-cycle progression, and also function as miRNA sponge to antagonize the latter functions and lead to the de-repression of miRNA endogenous target." (PMID 30598113, 2018). "Oncogenic role of lncRNA H19 has been demonstrated in diverse human solid tumors, and H19 expression was significantly upregulated in these cancer patients." (PMID 29643943, 2018). "The long non-coding RNA H19 is highly expressed in several cancers, and the functions of H19 vary among cancer cell types." (PMID 30410672, 2018). "Through searching the published literatures, six lncRNAs (ZFAS1, PRNCR1, GAS5, TUG1, linc-ROR, H19) which have been reported to be abnormally expressed in cancer were included in the present study." (PMID 29559565, 2018). "Taken together, these results support our proposal that H19 contributes to cell adhesion by regulating both the transition of epithelial cancer cells to a mesenchymal state and integrin expression." (PMID 30410672, 2018). "We performed next-generation sequencing data analysis and validated expression of three deregulated and cancer associated lincRNAs–MALAT1, H19 and FENDRR–in GIST and adjacent tissues." (PMID 30557328, 2018). "The expression levels of numerous lncRNAs are altered in several types of cancer, and several lncRNAs are already used as molecular tools for diagnosis and prognosis of cancer like H19, HULC and HOTAIR." (PMID 29755696, 2018). "This indicates that H19 can play a role in various cancers and other conditions where JAK-STAT signalling is important." (PMID 30567492, 2018). "Several studies have shown aberrant expression of H19 in multiple cancers including squamous cell carcinoma of head and neck." (PMID 29844862, 2018). "Strong evidence has proved that aberrant H19 DMR/ICR methylation by controlling CTCF6 binding sites led to LOI of IGF2/H19 and finally resulted in abnormal expression of IGF2/H19 in diverse human cancers." (PMID 29643943, 2018). "The involvement of H19 in cell adhesion and integrin expression in cancer cells has been reported in only a few previous studies." (PMID 30410672, 2018).
cancer (continued). "Here we selected six candidate cancer-related lncRNAs (ZFAS1, PRNCR1, GAS5, TUG1, linc-ROR, and H19) through articles that were previously reported to be dysregulated in cancer." (PMID 29559565, 2018). "H19 is an imprinted lncRNA, and has long been identified as an aberrantly expressed non-coding RNA in a great number of cancers, and has been shown to play multi-faceted roles during the tumourigenic process; and is considered to be a critical element in EMT." (PMID 29701689, 2018). "It appears that the H19-miR-675 lncRNA-miRNA interactions function in different cancer cell types by targeting different mRNAs." (PMID 29579063, 2018). "There are inconsistencies between various murine models which aim to define the role of H19 locus in cancer." (PMID 29972883, 2018). "Many studies have shown a strong association between H19 expression and dysregulated imprinting of the IGF2/H19 locus with carcinogenesis in several types of cancer, including HCC." (PMID 29495592, 2018). "Aberrant H19 imprinting is often seen in cancer as well and is thought to have an important role in cancer development." (PMID 30297886, 2018). "LncRNA H19, transcribed from chromosome 11p15.5, is becoming a hotspot in cancer research and is mainly located in cytoplasm." (PMID 29416703, 2018). "Among the roles previously demonstrated for H19 as a modulator of cancer cells, one mechanism of action in the nuclear compartment involves the epigenetic modulation of the expression of Nkd1, an inhibitor of Wnt pathway." (PMID 29643989, 2018). "Among the top deregulated lincRNAs, three previously cancer associated lincRNAs—MALAT1, H19 and FENDRR, were significantly upregulated in a discovery cohort." (PMID 30557328, 2018). "H19 gene, with the length of 2.3 kb and located in 11p15.5, containing five exons and three introns, which has been well accepted that lncRNA-H19 plays an important role in the development, migration, invasion, and metastasis of cancers." (PMID 29511035, 2018). "Lastly, aspirin markedly attenuates glycolysis and cancer stem-like characteristics by suppressing both H19 and PDK1." (PMID 29106390, 2018). "Association analyses revealed strong correlations between expression levels of lincRNA H19 and GIST-related oncogene ETV1 and cancer associated miR-455-3p." (PMID 30557328, 2018). "For instance, ANRIL, HOTAIR, and H19, have been reported to influence many processes in various cancers, including chromatin remodeling, transcriptional regulation, molecular trafficking, inflammation responses and oxidative stress." (PMID 30305026, 2018). "Several lncRNAs reportedly having crucial roles in cancer, including HOTAIR, MALAT1 and H19, have been reported to be linked to survival." (PMID 30038703, 2018). "To further investigate the relationship between H19 and cancer development, we summarized the effects of H19 on malignant phenotypes (including proliferation, differentiation, invasion, metastasis, and invasion) and its molecular mechanisms." (PMID 30219045, 2018). "H19 has been revealed to be upregulated in various carcinomas and to play important roles in the occurrence, development, metastasis, and prognosis of tumors." (PMID 29449695, 2018). "H19 is an imprinted oncofetal lncRNA, and has long been identified as an aberrantly expressed non-coding RNA in a great number of cancers with multi-faceted roles throughout tumourigenesis." (PMID 28430163, 2017). "The aberrant expression of H19 leads to the proliferation and migration of various cancers, such as gallbladder, gastric, and pancreatic cancers." (PMID 29299179, 2017). "Some meta-analyses focused on the association of lncRNAs such as MALAT-1, AFAP1-AS1, H19, and PVT1 and metastasis as well as prognosis with cancer; all analyzed only the lncRNAs detected in cancer tissues." (PMID 28146578, 2017).